DOT1L (DOT1 like histone lysine methyltransferase)
Diseases named in the same sentence as DOT1L in open-access papers (continued):
Sharing a sentence is not in itself a finding about the gene and the disease.
leukemia (continued). "Preclinical work on DOT1L inhibitors in both cell lines and mice transformed with KMT2A-rearranged leukemia demonstrated inhibition of tumor proliferation and leukemia regression." (PMID 32050659, 2020). "Previous studies have shown that DOT1L and ENL positively regulate HOXA9 expression in MLLr leukemia via direct occupancy on HOXA9’s promoter." (PMID 33001025, 2020). "In mammals, Dot1L (Dot1 (yeast)-Like) is essential for embryo viability, and enhanced activity of DOT1L enzyme is observed in mixed lineage leukemia (MLL)." (PMID 33104701, 2020). "DOT1L, a methyltransferase that catalyzes the methylation of histone H3 lysine 79 residues, is known to promote tumorigenesis in MLL-rearranged leukemia, with aberrant expression related to poor clinical outcomes." (PMID 33379275, 2020). "Another well-studied function of DOT1L is its pro-tumorigenic effect, especially in the MLL-rearranged leukemia, and targeting DOT1L has therefore been proposed as a potential therapeutic approach." (PMID 33363525, 2020). "In MLLr leukemia, the MAT2A product SAM serves as a substrate for many important methyltransferases like the H3K79 histone methyltransferase DOT1L or PRMT5, both involved in the pathogenesis of the disease." (PMID 32456310, 2020). "The histone 3 lysine 79 (H3K79) methyltransferase (HMT) DOT1L is known to play a critical role for growth and survival of MLL-rearranged leukemia." (PMID 32215184, 2020). "Recently, the methyltransferase DOT1L has emerged as a druggable target for this AML subgroup, since MLL fusions can recruit DOT1L and its mislocation induces aberrant H3K79 methylation and overexpression of leukemia relevant MLL target genes." (PMID 32698374, 2020). "Loss-of-function mouse models, as well as small molecular inhibitors of DOT1L, reported that KMT2A-rearranged leukemias are DOT1L dependent for proliferation." (PMID 31555628, 2019). "Various in vitro and in vivo experimental systems have shown that DOT1L and the interaction between DOT1L and MLL fusion partners is critical for development of leukemia in patients with MLL translocations." (PMID 31552175, 2019). "The pivotal role of DOT1L in MLL-r leukemia and its enzymatic specificity, have favored the search for chemical compounds directed against this molecule for use in leukemia treatment." (PMID 31727944, 2019). "Both compounds are potent inhibitors of DOT1L with IC50 values of 1.4 and 0.4 nM, respectively, inhibited the proliferation of MLL-rearranged leukemia cell line MV4-11 (IC50 = 85 and 128 nM, respectively), and were selective against a panel of 22 PMTs." (PMID 31817960, 2019). "Phase 1 clinical studies with pinometostat (EPZ-5676), an inhibitor of DOT1L activity, demonstrated the therapeutic potential for targeting DOT1L in MLL-r leukemia patients." (PMID 31727944, 2019). "Epizyme’s pinometostat, a highly selective DOT1L inhibitor, was the first KMT inhibitor to enter Phase I clinical trials for the treatment of leukaemia." (PMID 31791394, 2019). "In MLL-fusion expressing leukemia, a combinatorial effect of SETD2 downregulation and pharmacological inhibition of DOT1L was observed." (PMID 30818762, 2019). "Two recent studies highlight the possibility of targeting YEATS domains in MLL-rearranged leukemia, potentially synergizing with BET and DOT1L inhibition." (PMID 31747960, 2019). "Human DOT1L further interacts with AF10, an MLL-fusion partner, resulting in the upregulation of multiple leukemia-relevant genes, including HOXA9 and HOXA7." (PMID 30881380, 2019). "In MLL-rearranged leukemia, several MLL fusion proteins interact with DOT1L, which is a histone H3 lysine 79 (H3K79) methyltransferase, and induce transcription of target genes, e.g., HOXA9 and MEIS1." (PMID 31527484, 2019). "Consistent with this, a potent activator of SIRT1, SRT1720, was demonstrated to synergize with EPZ004777, a DOT1L inhibitor, and enhance anti-proliferative activity against MLL-r leukemia cells." (PMID 31157223, 2019).
leukemia (continued). "Pinometostat, which targets DOT1L, was investigated in phase I trials in adults with relapsed or refractory MLL-r leukemia (NCT01684150), and in pediatric patients with relapsed of refractory MLL-r leukemia (NCT02141828)." (PMID 30558227, 2018). "EPZ-5676, a small-molecule inhibitor of DOT1L, has been evaluated for MLL-rearranged leukemia in Phase I clinical trials (clinicaltrials.gov, EPZ-5676-12-001/NCT01684150/)." (PMID 29343685, 2018). "Subsequent studies with an improved DOT1L inhibitor, EPZ-5676, have exhibited complete regression of MLL-rearranged leukemia in a rat xenograft model." (PMID 30159125, 2018). "In our MLL-AF9 leukemia model studies, SALL4 appears to recruit both DOT1L and LSD1 to specific downstream target genes and modulate their H3K79me2/3 and H3K4me3 levels, thereby maintaining proper gene expression and leukemic survival." (PMID 29308206, 2018). "Recent studies have demonstrated that knockdown of DOT1L effectively reduced the H3K79 methylation level in AML cell lines and impeded leukemia cell proliferation." (PMID 29665865, 2018). "This in turn forms a docking site for BRD4 thereby facilitating the target gene expression and co-inhibition of DOT1L and BRD4 has been shown to act synergistically in targeting MLL-rearranged leukemias." (PMID 29240787, 2017). "DOT1L inhibitors can specifically target this altered gene expression and selectively kill MLL-leukemias." (PMID 28445939, 2017). "Given the critical functions of histone methylome in AML, the first HMT inhibitor targeting DOT1L, EPZ477759 and its second-generation derivative, EPZ567660 have been developed and tested for suppressing MLL leukaemia." (PMID 27593928, 2017). "Di-methylation of H3K79 mediated by DOT1L is involved in this process, as described in MLL leukemia, suggesting an unrecognized functional interplay between BRD4 and DOT1L." (PMID 28804523, 2017). "The adenosine derivative and its phenylurea analog (EPZ004777) showed very good inhibition and specificity for DOT1L, reduced leukemia-relevant gene expression and induced differentiation of MLL (mixed-lineage leukemia) leukemia cells." (PMID 28067760, 2017). "Similar mechanisms might be also functional among DNMT3A-mutated leukemias (right) where DNMT3A mutations perturb efficient CpG methylation at cis-regulatory sites leading to elevated histone acetylation and increased binding of DOT1L-associated complexes that harbor YEATS-containing AF9 and ENL." (PMID 29075615, 2017). "There are several selective small molecule inhibitors of DOT1L, including EPZ-5676, which is currently under clinical evaluation for treating MLL- rearranged leukemia (ClinicalTrials.gov identifier NCT02141828)." (PMID 28231254, 2017). "Exciting new data also comes from drugs developed to target leukemias harboring MLL1 translocations, BET inhibitors, and DOT1L inhibitors." (PMID 27723796, 2016). "These inhibitors block MLLr leukemia by targeting either transcription cofactors that physically interact with MLL1 (for example, WDR5) or MLL1 fusion proteins (for example, DOT1L and MENIN)." (PMID 27462455, 2016). "DOT1L inhibitors have been developed and are currently in clinical trials for the treatment of MLL-r leukemia." (PMID 27922451, 2016). "An earlier study showed DOT1L to be essential for HOXA9 and MEIS1 expression and the resulting leukemia driven by MLL-AF9." (PMID 23847761, 2013). "DOT1L inhibitors such as EPZ004777 and EPZ5676 that employ competitive SAM inhibition strategies impair tumor growth in PC models, with EPZ5676 advancing to clinical trials in leukemia." (PMID 41601922, 2026). "Though DOT1L has not yet been implicated in CML, its significant role in the development of MLL -rearranged (MLL-r) leukemia is supported by accumulated evidence." (PMID 40282457, 2025).
leukemia (continued). "As DOT1L emerged as an essential molecular drug target in acute leukemias harboring a KMT2A-fusion protein, small-molecule inhibitors targeting DOT1L were developed to reverse aberrantly expressed leukemic transcriptional programs in those leukemias." (PMID 40374809, 2025). "DOT1L, the sole histone H3K79 methyltransferase, is co-opted by KMT2A (MLL) fusion complexes to sustain HOXA/MEIS transcriptional circuitry in KMT2A-rearranged leukemias." (PMID 41347170, 2025). "Potent and selective small molecule inhibitors of DOT1L have been developed and tested in preclinical and early-phase clinical trials and showed good tolerability but rather modest efficacy in patients with MLL-rearranged leukemia." (PMID 40781484, 2025). "The first-in-class DOT1L inhibitor Pinometostat (EPZ-5676) provided proof-of-concept: treatment led to reduced H3K79 methylation and downregulation of HOX/MEIS1 expression in MLL-rearranged leukemia." (PMID 40651916, 2025). "Menin expression was also found to be correlated with the expression of the H3K79 histone methyltransferase DOT1L in human ovarian cancers, similar to MLL-rearranged leukemia and endocrine-resistant breast cancer cells, where menin regulates DOT1L activity in a pro-tumorigenic manner." (PMID 39336822, 2024). "Besides, Dex decreases DOT1L expression in Dex‐sensitive B‐lymphoma cells and MLL‐rearranged leukemia cells, but not in Dex‐insensitive acute monocytic leukemia cells, suggesting that DOT1L may be an underlying novel indicator of Dex sensitivity against hematological malignancies." (PMID 39307938, 2024). "We identified the phosphorylation of CBP by ATM, which confers the stability of CBP by preventing its proteasomal degradation, and characterised the acetylation of DOT1L by CBP, which mediates the high level of H3K79me2 for the expression of leukaemia genes in MLLr-AML." (PMID 38671157, 2024). "DOT1L and H3K79 methylation are critical players in MLLr leukaemia." (PMID 38671157, 2024). "HOXA9 plays a key role in KMT2A-rearranged (KMT2A-r) leukemia, mediated by binding of the KMT2A fusion protein to HOX gene promoters and recruitment of DOT1L H3K79 methyltransferases." (PMID 38601080, 2024). "DOT1L, the only methyltransferase for H3K79 in mammals known to date, methylates H3K79 to activate the expression of HOXA and MEIS1 in LSCs to support the occurrence of leukaemia and to maintain the growth of MLLr leukaemia cells." (PMID 38671157, 2024). "In MLLr leukemias, the N-terminal of the COMPASS family H3K4 methyltransferase MLL1 (KMT2A) is fused with the C-terminal of any one of many fusion partners, including subunits of the DOT1L complex (DOTCOM) and the super elongation complex (SEC)." (PMID 39403928, 2024). "In contrast, no change in the mRNA level of DOT1L was found in mouse Atm−/− LSCs or in human ATM knockdown MLLr leukaemia cells." (PMID 38671157, 2024). "Similarly, the proliferation of P31/FUJ, a human leukemia cell line harboring CALM-AF10 fusion, depended on ENL and DOT1L." (PMID 37031220, 2023). "To examine whether ENL, DOT1L, and MYST family KATs are required for CALM-AF10 leukemia cell proliferation, we performed CRISPR/Cas9-mediated competition assays on murine and human leukemia cells." (PMID 37031220, 2023). "In this case, based on the Drosophila model, gpp/DOT1L appears to rather oppose NUP98-HOXA9 function, underscoring the need to critically evaluate the use of DOT1L inhibitors across cytogenetically different subtypes of leukemia." (PMID 37720104, 2023). "Thus, in addition to forming SEC for transcription elongation, AHD can recruit DOT1L for hypermethylation of H3K79, which is characteristic and critical to MLL1-r leukemia." (PMID 35395864, 2022). "It is worth mentioning that a Dot1L and menin combinatory inhibitors approach has been already proposed for therapy of some hematological malignancies including NPM1-mutant and MLL-rearranged leukemias." (PMID 35850772, 2022).
leukemia (continued). "The catalytic inhibition of DOT1L leads to the transcriptional downregulation of these target genes and, ultimately, the abrogation of leukemia, indicating that H3K79me plays a critical role in maintaining MLL-r leukemias." (PMID 36497471, 2022). "Using a genetic approach, we compared the inhibitory effects of disrupting the AF9-DOT1L interaction or DOT1L enzymatic activity in leukemia cells harboring the MLL-AF9 oncoprotein as well as in non-leukemic adult bone marrow." (PMID 33562706, 2021). "The differential antiproliferation activities of compound 1 is consistent with its ability to suppress DOT1L/H3K79 methylation and SEC regulated gene expression, which are critical to MLL-r leukemia and Myc-driven blood cancer, but largely dispensable to other solid tumor cells." (PMID 34373735, 2021). "With a Ki of 0.08 nM, pinometostat was nearly four-times more potent against DOT1L as EPZ004777, as well as displaying improved potency for inhibiting MLL-rearranged leukaemia cell proliferation, abrogating H3K79me2, and reducing the expression of MLL-fusion target genes." (PMID 34458810, 2021). "Furthermore, when we coupled sc-Tiling with three-dimensional structural modeling, we discovered a self-regulatory R domain in DOT1L that modulates chromatin interaction, enzymatic activation, and therapeutic sensitivity in MLL-r leukemia." (PMID 34210975, 2021). "Ablation of H3K79 methylation through knockout or pharmacological targeting of DOT1L abrogates the MLL-fusion target gene expression profile, selectively induces apoptosis and differentiation of leukemia cells in culture and dramatically extends the survival of mice in xenograft experiments." (PMID 34263728, 2021). "Pinometostat is a first-in-class inhibitor of the DOT1L (disrupter of telomeric silencing 1-like) histone methyltransferase, an enzyme involved in the survival and proliferation of mixed lineage leukemia (MLL)-rearranged leukemia cells." (PMID 34680226, 2021). "In addition, genes bound by the histone methyltransferase DOT1L and downregulated upon Menin inhibition in KMT2A-MLLT3 leukemia were found to be enriched in Men1−/− versus Men1wt MN1-driven AML." (PMID 33542482, 2021). "Selective inhibitors of DOT1L with cellular activity (EPZ004777 and SGC0946) have been described, and a further optimized inhibitor (EPZ-5676) has even advanced to clinical trials in MLL-rearranged leukemia, where fusion proteins of MLL with a variety of partners recruit DOT1L to a set of genes (e." (PMID 32215184, 2020). "Collectively, these pre-clinical reports provided proof that pharmacological targeting of DOT1L could be an effective and selective treatment approach in MLL-rearranged leukemia." (PMID 33371192, 2020). "Recent studies have reported that additional leukemia subtypes lacking MLL-r are sensitive to DOT1L inhibition." (PMID 32698374, 2020). "The DOT1L inhibitor Pinometostat (EPZ − 5676) exhibited modest clinical activity in a phase I study, which paves a road for further exploration of combination therapies in leukemia." (PMID 32690020, 2020). "Moreover, CBP inhibitors and DOT1L inhibitors (that inhibit DOT1L enzymatic activity) or other targeted chemotherapies provide new opportunities for combinatorial CRC treatment and potentially other cancers such as leukemia." (PMID 32042335, 2020). "Given the fact that DOT1L is not required in normal tissues, pharmacological inhibition of DOT1L could be a highly selective treatment strategy in MLL-rearranged and MLL-dependent leukemia." (PMID 33371192, 2020). "Recently, DOT1L and PRMT5 have been identified as suitable targets with only minor side effects for the treatment of poor prognosis MLLr leukemia and we could demonstrate that the combination of both resulted in synergistic effects." (PMID 32456310, 2020). "DOT1L is an established preclinical target in MLL-rearranged leukemia, and some degree of clinical activity was observed with the first candidate that was tested in leukemia trials." (PMID 32215184, 2020).
leukemia (continued). "The results showed that LAMP5-AS1 knockdown could affect the methyltransferase activity of DOT1L and prevent the H3K79me2/3 at the most of MLL fusion target genes in leukemia." (PMID 32552847, 2020). "However, the aberrant recruitment of DOT1L by a majority of KMT2A-fusion partners results in an inappropriate hypermethylation and overexpression of downstream, targeted genes that promote leukemia." (PMID 32050659, 2020). "Although there is a new controversy about whether DOT1L is necessary for MLL LSC maintenance, the essential role of DOT1L in sustaining MLL leukemia cell self-renewal ability is undisputed." (PMID 32552847, 2020). "Preclinical studies revealed that DOT1L inhibition specifically reduces H3K79 methylation and expression of MLL target genes leading to reduction of proliferation and viability as well as increased differentiation of leukemia cells both in vitro and in vivo." (PMID 31552175, 2019). "They found that combined targeting of both DOT1L and BRD4 using SGC0946 (a small-molecule inhibitor of DOT1L) and I-BET, respectively, resulted in growth inhibitory synergy against MLL-r cell lines, primary human leukemia cells, and mouse leukemia models." (PMID 31157223, 2019). "In addition, further preclinical studies demonstrated that combining DOT1L and menin inhibition enhances the treatment efficacy in MLL-rearranged leukemia models." (PMID 31803695, 2019). "DOT1L methylates histone H3K79 and is aberrantly regulated in MLL‐rearranged leukemia." (PMID 31304633, 2019). "Interestingly, several recent studies have demonstrated the functional role of DOT1L in the development and progression in MLL-r type leukemia." (PMID 29665865, 2018). "Collectively, these results suggest that while DOT1L regulates leukemia cell proliferation it does not play a major role in regulating normal melanocyte growth." (PMID 29343685, 2018). "A DOT1L-specific methyltransferase inhibitor, EPZ004777, was shown to extend survival in a mixed lineage leukemia (MLL)-rearranged leukemia mouse model and attenuated global H3K79 methylation in human leukemia cell lines." (PMID 30159125, 2018). "For instance, DOT1L targets the MYB gene locus in the MV411 leukemia cells but not in the C021 or C025 melanoma cells." (PMID 29343685, 2018). "Inhibition of DOT1L activity or disrupting the interaction between DOT1L and MLL fusion partners are potential therapeutic strategies for the treatment of MLL-fusion-related leukemias." (PMID 29495487, 2018). "Recent studies have suggested that EPZ-5676 exhibits therapeutic effects in leukemia by inhibiting the methyltransferase activity of DOT1L, however this has never formally been proven to be an on-target effect using a resistance-conferring allele of DOT1L." (PMID 28231254, 2017). "It is therefore no surprise that DOT1L inhibitors are currently extensively evaluated for their efficacy in MLL-rearranged leukemias." (PMID 29240787, 2017). "Accordingly, inhibition of DOT1L led to dramatically decreased binding of BRD4 to chromatin, and the combination of a bromodomain inhibitor and a DOT1L inhibitor was synergistically active against MLL-r leukemias both in vitro and in vivo." (PMID 28232907, 2017). "A small molecule inhibitor of Dot1L (EPZ-5676 or pinometostat) has been developed by Epizyme, Inc. and is being studied in early clinical trials in both adult and pediatric patients with MLL-r leukemias (NCT01684150 and NCT02141828)." (PMID 28232907, 2017). "Moreover, LSD1 inhibitors worked synergistically with inhibition of DOT1L, a histone H3 lysine 79 (H3K79) methyltransferase, against MLL-rearranged leukemia." (PMID 26970896, 2016). "While BRD4 and the H3K79 methyltransferase DOT1L do not physically interact, studies in mixed lineage leukemia have suggested DOT1L methylates and establishes a chromatin state that is permissive for acetylation and BRD4 recruitment." (PMID 27698495, 2016).